CD4 (CD4 molecule)
Diseases named in the same sentence as CD4 in open-access papers (continued):
Sharing a sentence is not in itself a finding about the gene and the disease.
cancer (continued). "Naturally occurring NY-ESO-1-specific CD4+ and CD8+ T cell responses were typically detected only in patients who had serum antibody against NY-ESO-1, indicating that spontaneous immune responses against NY-ESO-1 in cancer patients with NY-ESO-1 expressing tumors were highly integrated." (PMID 21858191, 2011). "Thus, spontaneous CD4+ T-cell responses to ESO in cancer patients are prevalently of TH1 type and not Treg." (PMID 21829534, 2011). "Among the four peptides, the EGFR729–738 peptide was recognised by the majority of patients' sera, but by none of the sera of the HDs, suggesting that CD4+ T cells of cancer patients may be involved in the antipeptide-specific IgG production." (PMID 15083186, 2004). "Interestingly, high proportions of exhausted genes were observed in Treg and CH25H+ CD4+ T cells in EGC, suggesting that Treg and CH25H+ CD4+ T cells are likely important T‐cell subsets for maintaining immune balance in the microenvironment of early‐stage cancer." (PMID 40860436, 2025). "The induction of apoptosis by the inhibition of SLC7A5 or dietary L-Leu restriction is a mechanism that might contribute to control CD4 T cell-mediated immune response which has not been described previously, although this effect has been well documented for cancer cells." (PMID 40399490, 2025). "Additionally, in two different case series studies of PLWH on cART and treated for a variety of malignancies, an excellent tolerability of anti-PD-1 and/or anti-PD-L1 therapy was observed, and all patients showed stable CD4 T-cell counts and no reactivation of HIV load during ICI therapy." (PMID 38130714, 2023). "However, most other cancers showed a negative correlation with CD4+ T cells, which may be one of the reasons why the high expression of ESPL1 in THYM exhibited a better prognosis." (PMID 37006282, 2023). "Interestingly, the enrichment of CD8+ T cells and much more aggregation of CD4+ T cells, CD49b+ NK cells were observed in CRC mice accepted with FMT, as well as reduced population of Foxp3+ Treg cells, F4/80+ macrophages, indicating the augmentation of anti-cancer efficacy." (PMID 37143538, 2023). "To test this hypothesis, we utilized a well-known immune cell abundance score in various cancer types, called TIMER score, which was pre-calculated and made available for six immune cell types (B cell, macrophage, dendritic cell, neutrophil, CD4+ T cell, and CD8+ T cell) for TCGA data." (PMID 38188295, 2023). "A variable proportion of individuals fails to achieve a CD4+ T cell number above 500/μL, despite chronic suppression of HIV-1 replication, and this suboptimal recovery increases the risk of many comorbidities (heart, renal, metabolic, bone diseases, and cancers) as well as all-cause mortality." (PMID 36672667, 2023). "Also, one of the main functions of CD4+ T cells is the regulation of antitumor immune responses by suppressing the proliferation of CD8+ T cells, which may lead to an immune escape and to the proliferation of cancer cells." (PMID 36606194, 2022). "Thus, CD4+ T cells help initiate a gene expression program in CD8+ T cells that enhances CTL function by improving their migratory potential and downregulating the expression of their co-inhibitory receptors resulting in increased antitumor efficacy of cancer therapeutic vaccination." (PMID 35008422, 2022). "Indeed, whereas the live vaccine induced lethal ascites in CD11c‐DTR mice in which DCs were transiently ablated, it failed to do so in mice with an intact DC pool, indicating that MHCII‐expressing cancer cells could not directly prime CD4+ T cells." (PMID 35959554, 2022). "Therefore, we could not assess the significance of CXCL13 derived from CD4+ T cells on the formation of TLS in our mouse cancer models." (PMID 35552285, 2022).
cancer (continued). "Similarly, lower doses of peptide antigen, rather than high doses, preferentially primed high avidity CD4+T cells for cancer immunotherapy, stimulating both antibody responses and cytotoxic T cell responses, instead of skewing the response toward one arm of the immune system." (PMID 34578257, 2021). "Indeed, we found that rSmeg-hMIF-hIL-7 elicited an enhanced CTL response against CD4+ and CD8+ T cells cocultured with infected dendritic cells compared with rSmeg expressing h-MIF alone or h-IL-7 alone, suggesting an adjuvant effect of IL-7 in cancer immunotherapy." (PMID 34389619, 2021). "This study opens up new important questions for further investigations, including whether cancer cells without PD-L1 expression can induce CD4+ T cell exhaustion in a similar or different way and whether the blockage of PD-1/PD-L1 interactions could reverse CD4+ T cell exhaustion." (PMID 34439305, 2021). "In addition, many CD45RA-Foxp3 non-suppressive Treg cells in human cancer could differentiate into memory effector CD4+ T cells." (PMID 34489925, 2021). "Finally, CD4 T cells can also mediate direct cytotoxic responses through IFN-γ and TNF secretion, production of cytolytic granules or expressing ligand of tumor necrosis factor (TNF) superfamily molecules including FasL or TRAIL leading to cancer cell apoptosis when engaged with their receptors." (PMID 33329566, 2020). "However, due to differences in T-cell composition and the overall intestinal microenvironment in humans and transgenic mice, activation of tissue-resident memory CD4+ T cells by antigen-presenting ILCs in the human mucosa cannot be ruled out, especially in the context of inflammation or cancer." (PMID 32341343, 2020). "Moreover, CCL14 expression significantly correlates with the infiltration levels of CD4+T cells in 28 cancer types, B cells in 19 cancer types, CD8+T cells in 15 cancer types, dendritic cells in 16 cancer types, macrophages in 19 cancer types, and neutrophils in 17 cancer types." (PMID 31927532, 2020). "Furthermore, vaccination within TAE-exosome loaded T cells (exosome-T) has the ability to counteract CD4+CD25+ Treg cell-mediated immunosuppression and to trigger long-term CTL memory, providing attractive strategies for inducing immune responses against human cancers." (PMID 33183286, 2020). "Thus, optimal provision of CD4+ T-cell help may be critical to fully engage self antigen-specific CD8+ T and B cells and produce meaningful antitumor immunity and clinical efficacy with cancer vaccines targeting GUCY2C and other self antigens." (PMID 31010434, 2019). "CD4+CD25+FoxP3+ regulatory T cells are crucial to the maintenance of tolerance in normal individuals, and, so far gathered evidence indicates that presentation and progression of certain immunological disorders as well as the progression of cancer may be a function of Treg cell behavior." (PMID 31288845, 2019). "Alternative replacement of anti-HER2 CD4+ Th1 would be to administer Th1 cytokines such as systemic IFN-γ or IFN-γ-inducing agents like STING and Toll like receptor agonists, may be combined with anti-HER2 targeted therapies as an immunotherapeutic approach to treat HER2 positive cancer patients." (PMID 29796172, 2018). "Interestingly, we observed not only an overall increase in CXCL9 in cancer, but also a significant increase in ER‐negative subtypes compared to luminal A cancers, and these levels correlated significantly with levels of the TIL‐related markers CD8A, CD4, and CD5." (PMID 30019538, 2018). "Thus, in addition to a role in MHC class II-restricted presentation for stimulation of CD4+ T cell responses, GILT plays a role in cross-presentation of exogenous antigens on MHC class I and cross-priming of CD8+ T cells, which is important in both viral infection and cancer." (PMID 24409178, 2013).
cancer (continued). "Moreover, the percentage of FOXP3+ cells within the CD4+CD127low T-cell population was always higher than within the CD4+CD25high population, suggesting that previous data only assessing a CD4+CD25high phenotype have underestimated the absolute increase of FOXP3+ Treg cells in cancer patients." (PMID 21904560, 2011). "In both TILs and blood lymphocytes, the Tac antigen was consistently present on greater numbers of CD4+ T lymphocytes than on the CD8+ T lymphocytes (P less than 0.001) and as this is a component of the interleukin 2 (IL-2) receptor this may be of relevance to the use of IL-2 in TIL cancer therapy." (PMID 2124138, 1990). "Histopathology revealed infiltration of CD4+, CD8+ lymphocytes, and CD68+ macrophages without cancer cells." (PMID 41768084, 2026). "Human leukocyte antigen (HLA) plays a central role in rejecting endogenous non-self proteins (e.g. cancer neoantigens) by activating CD8+ cytolytic T cells via the Class I system (HLA-I) and CD4+ helper T cells via the Class II (HLA-II) system." (PMID 42266824, 2026). "However, given the diverse functions and responses of different CD4+ T cell subtypes in cancer surveillance, and the requirement for additional conditions to activate CD4+ T cells, it's possible that some subpopulations of CD4+ T cells may be upregulated, but this is not yet well understood." (PMID 39482885, 2025). "Combined with reduced CD4+ T-cell-mediated immune surveillance, these mechanisms facilitate malignant transformation and progression of non-AIDS-defining cancers such as NSCLC in PWH." (PMID 41304899, 2025). "Interestingly, for a partially activated CD4+ T cell with no self-reactivity, it is possible that this antigen may come from a transformed or cancer cell, or from a covalently modified component of a normal cell, or from a somatic cell which produces a mutant antigenic protein." (PMID 41296449, 2025). "Spleens of triple therapy animals showed significantly more CD8 + cells, with non-significant increases in CD4 + and MHC-II + also present, supportive of generation of systemic anti-cancer immunity following chemotherapy, ICI and virotherapy." (PMID 40465005, 2025). "In general, a positive correlation was observed between NCBP2 and various immune cells, such as MDSC, progenitors of lymphoid, CD4+ T cell, CAF, neutrophils and monocytes, however a negative correlation was identified with NKT cells in various cancers." (PMID 40124611, 2025). "Unlike CD4+ T cells, which operate under MHC-II restriction, CD8+ T cells can activate CD40 on virtually any cell, including cancer cells, upon recognizing specific peptide/MHC-I complexes with their T cell receptor (TCR)." (PMID 40397730, 2025). "Immunohistochemical analysis of CD4 and CD8 T cells in a tissue microarray (TMA) containing 92 pairs of HCC cancer tissue and adjacent nontumor tissue samples was performed." (PMID 37948019, 2024). "While individuals without cancer and patients with cancer treated with CT alone harbor monofunctional spike-specific CD4 T cell producing TNF, the majority of monofunctional CD4 T cells in patients treated with IT alone or in combination with CT produce IFNγ." (PMID 39257577, 2024). "In most cancers, NXPH4 exhibited a positive link to follicular helper T cells, M0 macrophages, and plasma cells, and a negative link to CD8+ T cells, CD4+ memory T cells, and monocytes." (PMID 38613793, 2024). "In many cancer types, ASPP1 exhibits a negative correlation with activated CD4+ T cells, gamma delta T cells, CD8+ T cells, and memory B cells." (PMID 39830645, 2024). "Additionally, many antibody-based bispecific therapies bind to cancer surface antigens on-target cells rather than pHLA which will alter their mode of action, as, unlike pHLA, these antigens are unable to recruit CD4 and CD8 co-receptors, and so may display significantly different optima." (PMID 37930865, 2024).
cancer (continued). "Other types of immune cells, such as CD4+, CD8+, and exhausted CD8 + T cells, also interacted with cancer cells; however, these interactions are not as strong as interactions between DCs and macrophages with cancer cells." (PMID 38872167, 2024). "Since most cancer cells do not express MHCII class molecules (HLA-DR), they cannot be directly recognized by CD4+T cells." (PMID 38279145, 2024). "Moreover, after being treated with the HRMTF NPs, the intratumoral helper T cells (CD3+CD4+) and cytotoxic T cells (CD3+CD8+) were both largely increased relative to those in the control group, demonstrating that the HRMTF NPs could finally stimulate the local immune system for cancer therapy." (PMID 36930774, 2023). "Consistent with cancer patient data, responders (increased IL-2) exhibited a significantly lower IRC in CD4 and CD8 T cells compared to nonresponding patients." (PMID 38055623, 2023). "γδT is a CD4-negative and CD8-negative T-cell subgroup having both anti- and pro-tumoral functions during cancer progression." (PMID 37353799, 2023). "In our study, gender did not seem to influence the cell counts of CD45+, CD3+ T, CD3+CD4+ Th, CD3+CD8+ CTL, the percentage of CD3+CD45+ cells and CD3+CD8+ CTL in cancer patients." (PMID 38102684, 2023). "CD4+ T cells do not generally express NKG2D, but its expression is inducible under pathological conditions, including rheumatoid arthritis and cancer." (PMID 37626965, 2023). "Although NKG2D is not normally expressed by CD4+ T cells, NKG2D+ CD4+ T cells can accumulate in cases of chronic inflammation or cancer." (PMID 37626965, 2023). "Significant levels of IL-2, IFN-ɣ and TNF-α were detected in supernatants of CD4+ nfP2X7-M-CAR-T cells co-cultured with MDA-MB-231 and U87 cancer cell lines, but not when co-cultured with either SK-ND-Z or K562 cells." (PMID 37684239, 2023). "Particularly, as the pivotal immune cells for targeting cancer, the immune abundances of CD8+ T, CD4+ T and NK cells did not present significantly differences between high- and low-TMB groups." (PMID 35568842, 2022). "Brand and colleagues showed that the production of lactic acid by cancer cells limits CTL and NK cell activation and impairs IFN-γ production; curiously this pattern was not present in CD4+ and IL-17+ CD4+ (Th17) T cells." (PMID 36330529, 2022). "The only study using CD4 and CD25 rather than FOXP3 to delineate Tregs did so because the aim was to investigate FOXP3 not only in Tregs, but also in cancer cells." (PMID 35740658, 2022). "CAR affinity and cancer antigen expression, but not CAR T-cell dose or CD4+:CD8+ ratio, dictate this difference." (PMID 35903149, 2022). "Cells were classified into different cell types based on cell identity markers for cancer/epithelial cells (positive for cytokeratin AE1 or PCK26), immune cells (positive for CD3, CD4, CD8, or CD45), and other stromal cells negative for any of these markers." (PMID 34754079, 2022). "A single-cell transcriptional analysis of four independent datasets indicated that GCH1 had a relatively high expression in monocytes/macrophages, B cells, CD4+ T cells, and CD8+ T cells, but low or no expression in malignant tumor cells." (PMID 36072600, 2022). "For example, not all clusters were uniformly decreased in cancer, with a population of TBET- memory CD4 T cells (P1_28) and CD14- CX3CR1 + monocytes (P2_25) being elevated in cancer." (PMID 36307410, 2022). "Further, the non-leukemic CD8+ and CD4+ T cell repertoires in T-LGLL were more mature, cytotoxic, and clonally restricted than in other cancers, in RA, and in healthy controls, suggesting the strong immune-editing capacity of a driving antigen." (PMID 35411050, 2022). "Liu and others demonstrated that CD4+ T cells, but not CD8+ T cells, are essential for tissue healing and remodeling of the blood vasculature in cancer." (PMID 36589226, 2022).
cancer (continued). "In recent years, studies have indicated that CD4+T cells, CAF, MDSC, neutrophils, and macrophages play a key role in cancer immunotherapy; the role of immune cells in cancer therapy should not be overlooked." (PMID 35401558, 2022). "In contrast, advanced cancer cells are no longer capable of initiating a differentiation program and they respond to TSLP-activated CD4+ T cell immunity by undergoing senescence." (PMID 36467403, 2022). "In most cancers, CD274 and PDCD1LG2 showed significantly positive relationship with memory-activated CD4+ T cells but a negative correlation with naive CD4+ T cells." (PMID 36276934, 2022). "Avasimibe inhibited the cholesterol esterification of CD8+ TILs rather than cancer cells and reversed the ratio of CD8+/CD4 T cells, especially decreased CD4+CD25+FOXP3+ Treg cells infiltration in the TME." (PMID 36275711, 2022). "Of note, m7G scores were negatively correlated with CD4 T cells, CD8 T cells and NK cells but positively correlated with Treg cells in most of cancer types, while the relevance with naïve CD4 and CD8 cells were not obviously seen through cancers." (PMID 36092891, 2022). "Pan-cancer TME were categorized into two groups: the inflamed and the non-inflamed by the signature, and CD4/8 + T-cells tended to infiltrate the inflamed." (PMID 35812726, 2022). "The density of CD4+ T cells, CD8+ T cells, and CD20+ B cells in the CT and IM areas of the cancer tissue was similar between the 6 CAM patients and 12 non-CAM patients." (PMID 36687449, 2022). "While we could not distinguish between Th1 and Th2 CD4+ T cells in our data, polymeric nanoparticles have previously been reported to induce Th1 phenotypes, motivating further study on how cargo-free nanoparticles stimulate anti-cancer adaptive immune responses." (PMID 36479083, 2022). "Epacadostat significantly increased the migration and infiltration of NK and CD4+ T cells, but not CD8+ T cells, towards the cancer cells." (PMID 35359980, 2022). "We then analyzed the transcriptome of CD4+, CD8+ and Tregs from malignant and nonmalignant samples and identified common genes across the different types of cancer for each T-cell subset." (PMID 36232369, 2022). "A cell cluster expressing CD3, but not CD4 or CD8 (Cluster 20), was observed at higher frequency in cancer patients relative to HDs." (PMID 34090509, 2021). "The same pattern, although not significantly different, was observed in activated CD4+ T cells; 15.5%–18.8% of HIV-1 integration sites were in cancer-related genes." (PMID 33784259, 2021). "The binding of the BRM subunit was found in the promoter region of PD-L1 only in restimulated CD4+ T cells, without co-cultivation with MDA-MB-231 cancer cells." (PMID 34439305, 2021). "A population of cells of the size of lymphocytes, but negative for CD3, CD4, or CD8 expression (Cluster 24 + 29), was significantly less represented in cancer patients relative to HDs." (PMID 34090509, 2021). "The guidance recommends that patients with CD4+ T-cell counts ≥ 350 cells/μL and without AIDS-defining opportunistic infections within the past 12 months be eligible for any cancer trial." (PMID 33758321, 2021). "The finding of significantly less CD8+ and CD4+ T cells in the spleens explanted from mice in the PD-1 monotherapy group supports the conclusion that PD-1 monotherapy was not beneficial for the anti-cancer immune response, and may in fact have been detrimental." (PMID 33772035, 2021). "Equally fundamental are screening programs aimed at identifying oral, cervical and anal precancerous and cancerous lesions, regardless of the status of HAART treatment, CD4 + T cell count and viral load." (PMID 34501585, 2021). "But the positive relationship of LEPROT and memory CD4+ T cells resting, and the negative relationship of LEPROT and Th1 seemed to be strong and consistent across most cancer types." (PMID 34804118, 2021).